ENSG00000270066 (small Cajal body-specific RNA 2)
Gene: Long non-coding RNA gene on chromosome 1 (109,100,094 to 109,103,279, forward strand). Ensembl gene ENSG00000270066.
Gene Ontology:
Biological process: RNA processing
Cellular component: nucleolus